PVT1 (Pvt1 oncogene)
Diseases named in the same sentence as PVT1 in open-access papers (continued):
Sharing a sentence is not in itself a finding about the gene and the disease.
cancer (continued). "Gene expression profiling interactive analysis and a comprehensive resource for lncRNAs from cancer arrays databases were used to analyze lncRNA PVT1 expression and CRC prognosis, respectively." (PMID 38837682, 2024). "Altogether, findings indicated that DLC1 (deleted in liver cancer 1) and PVT1 genes are potentially involved in the Hippo signaling pathway." (PMID 38226210, 2024). "PVT1 and the circularization of the exon 2 of the PVT1 gene (circPVT1), an alternative transcript, have been reported to enhance malignant cells and hinder the immune response to the tumour during cancer progression." (PMID 38384455, 2024). "PVT1 functions as an oncogene by inhibiting cancer cell apoptosis, promoting cell proliferation, and affecting tumor invasion and metastasis generation." (PMID 38792557, 2024). "Similar to its target mRNA, PVT1 is also an oncogene, since the transcript and its locus share distinct functions in cancer." (PMID 39123456, 2024). "Despite some basic researches of PVT1-MYC duet suggested its role in cancer progression, the clinical relevance of PVT1, the potential regulatory networks of PVT1-MYC duet and its prognostic value remained to be elucidated, especially in large patient cohorts." (PMID 39376555, 2024). "Plasmacytoma variant translocation 1 (PVT1), a long non-coding RNA, plays an oncogenic role in various cancers." (PMID 38534356, 2024). "Ketamine, a dissociative anaesthetic mainly used for pain management in cancer, promoted anti-proliferative status in cancer cells by modulating the production of lncRNA PVT1." (PMID 40176927, 2024). "Apart from their role in cancer, it is worth mentioning that the PVT1–MYC interactions were also found to participate in diabetes." (PMID 39123456, 2024). "The plasmacytoma variant translocation 1 (PVT1) lncRNA, located on human chromosome 8q24, is co-amplified with MYC and has been identified as an oncogene in several cancers." (PMID 39015773, 2024). "For instance, a recent study pointed out a panel of 8 well-studied lncRNAs with 10 driver mutations from a lncRNA 112 census with known roles in cancer: DLEU2, GAS5, MONC, NEAT1, PINT, PVT1, SLNCR1, and XIST." (PMID 38292185, 2024). "A CRISPR interference (CRISPRi) screen of non-coding regions near the MYC locus found the promoter of nearby PVT1, which is subject to structural rearrangements in cancer, to be a non-coding tumor suppressor element." (PMID 37415185, 2023). "PVT1 and CCAT1 were implicated in the pathogenesis of certain cancers, according to data extracted from the Lnc2Cancer and LncRNA Disease databases." (PMID 36624401, 2023). "Studies have shown that PVT1 participates in multiple signaling pathways in cancer stemness, including the STAT3, PI3K/AKT, YAP1, and TGFβ pathways." (PMID 36894542, 2023). "Recently, a large number of studies have shown that lncRNA PVT1 is closely related to the occurrence and development of many malignant tumors." (PMID 36941464, 2023). "Both PVT-1 and c-Myc originate from 8q24.21 chromosomal region and are frequently copy-number gained in many human cancers." (PMID 38933287, 2023). "PVT1 was found in these studies to increase proliferation and metastasis of the cancer cells, suggesting its potential oncogenic role." (PMID 36624401, 2023). "Increasing evidence supports that PVT1 acts as an oncogene and regulates the phenotypes of cancer cells in multiple cancers." (PMID 36760720, 2023). "MiR-15b-5p has been reported to function as both oncogene and tumor suppressor in several human cancers, while is sponged by lncRNAs, PVT1- and MALAT1-lncRNAs among them." (PMID 37486375, 2023). "The tumor-suppressor function of the PVT1 promoter is also consistent with its recurrent translocations and deletions in human cancers." (PMID 38933287, 2023). "Long-non-coding RNA PVT1 (lncRNA PVT1) can be used as an oncogenic regulatory non-coding RNA (ncRNA) for many cancers." (PMID 36941464, 2023).
cancer (continued). "Regulation of PVT1/CircPVT1 in cells through genomic amplification, rearrangement, or increased transcription provides an advantage for cancer cell proliferation." (PMID 37573419, 2023). "To explore the molecular mechanism of PVT1 effect on HNSCC cancer cell stemness, we investigated the subcellular localization of PVT1 using a nuclear and cytoplasmic separation assay." (PMID 36894542, 2023). "In this study, we identified that lncRNA PVT1 regulates cancer stemness, metastasis, and anti-tumor immunity by controlling the DNA damage response and the miR-375/YAP1 axis." (PMID 36894542, 2023). "YY1 also promotes PVT1 expression via binding to its promoter to further affect autophagy through the mTOR pathway, leading to increased invasion and adhesion activity in cancer." (PMID 37724907, 2023). "It has therefore been verified that circRNAs take part in many kinds of cancer, particularly in the context of some drug resistance, such as for circ-pvt1, in promoting pacaxel resistance in GC." (PMID 35415017, 2022). "The lncRNA plasmacytoma variant translocation 1 (PVT1) oncogene, located at chromosome 8q24.21, is upregulated in various cancers, including PC." (PMID 35565245, 2022). "PVT1 was found in TEV of different cancers and contributes to the exosome secretion of tumour cells." (PMID 36011012, 2022). "Amplification of chromosome 8q24, which circPVT1 and lncRNA PVT1 locate on, is frequently observed in a variety of cancers including NPC." (PMID 36199071, 2022). "The PVT1/miR-143/HK2 axis represents the leading target candidate for therapies to regulate cancer metabolism and block tumour progression in GBC." (PMID 34754096, 2022). "Recent advancements have led to increasing insights into the critical roles of PVT1 in cancer initiation and progression." (PMID 36052265, 2022). "PVT1-coding gene has been found to be hyper-regulated in several cancers, including ovarian cancers." (PMID 35456025, 2022). "PVT1 is involved in various cancer progressions, such as proliferation, migration, or chemoresistance." (PMID 35256612, 2022). "This review comprehensively describes PVT1 expression in various cancers and presents novel approaches to the diagnosis and treatment of cancer." (PMID 36195846, 2022). "Here, we aimed to identify new biomarkers and therapeutic targets by summarizing the mechanisms of PVT1 in various cancers." (PMID 36195846, 2022). "PVT1, which is transcribed 52 kilobases downstream of MYC, is co‐amplified with MYC in many cancers and its increased expression is associated with a poor prognosis." (PMID 34668345, 2022). "Although PVT1 has been widely studied in a variety of cancer research, its role in DN is poorly understood." (PMID 36359234, 2022). "Multiple studies have clarified that the expression of PVT1 is lower in normal tissues but higher in various malignant cancer tissues and cancer cell lines, promoting tumor progression." (PMID 35664988, 2022). "The lncRNA plasmacytoma variant translocation 1 (PVT1) is encoded by PVT1 gene, and is usually highly expressed in various malignant tumor tissues or cells, while the expression level is low in normal tissues." (PMID 35794862, 2022). "LncRNA PVT1 has been known to play a critical role in oncogenesis and progression in a variety of human cancers." (PMID 36438563, 2022). "Circ-PVT1 has been reported as a proliferative factor in many cancers, such as gastric, colorectal, and esophageal cancers." (PMID 36358938, 2022). "The majority of studies in the past have focused on the relationship between PVT1 and the occurrence and development of various cancers." (PMID 35036445, 2022). "PVT1 is usually overexpressed in cancers to accelerate cancer growth and metastasis and inhibit cancer cell apoptosis." (PMID 35706414, 2022). "Although the oncogenic functions of PVT1 are widely reported in a range of cancers, its roles in other diseases are poorly understood." (PMID 36359234, 2022).
cancer (continued). "The most common mechanism of PVT1 in various cancers is regulation of the relevant signaling pathways by competitive endogenous RNA (ceRNA), which promotes the occurrence and development of cancer." (PMID 36195846, 2022). "Our studies using the ID8Trp53−/− cells in immunocompetent models are also highly pertinent, as PVT1 was recently reported to be significantly correlated with CD8 T-cell infiltration in several cancer types." (PMID 35820706, 2022). "The expression level of PVT1 was significantly and negatively correlated with miR-423-5p in cancer tissues." (PMID 35270630, 2022). "LncRNA PVT1 promotes cancer initiation and progression by acting as a competing endogenous RNA (ceRNA), activating STAT3 signaling or KAT2A acetyltransferase, or interacting with myelocytomatosis oncogene (MYC)." (PMID 36713226, 2022). "Further expression analysis on TCGA data showed that PVT1 transcripts were extremely higher in cancer tissues of COAD and READ, compared with that in normal tissues." (PMID 36266267, 2022). "To evaluate in detail PVT1 expression and amplification in broad cancer types, we evaluated The Cancer Genome Atlas (TCGA) datasets using cBioportal." (PMID 35820706, 2022). "PVT1 is a long noncoding RNA located on 8q24.21 which is lowly expressed in normal cells and tissues while being abnormally up-regulated in malignant tumor tissues and cells." (PMID 36295083, 2022). "PVT1 is documented to be involved in a variety of cancers development and plays a major role in regulating the efficacy of cancer chemotherapy." (PMID 35433465, 2022). "In recent years, three lncRNAs located by the five positive association SNPs found in this study, namely HOTAIR, PVT1 and EGFR-AS1, have been reported to be involved in the occurrence and development of a variety of cancers through the ceRNA mechanism." (PMID 36418931, 2022). "PVT1 is abnormally overexpressed in a variety of cancers and often promotes the occurrence, progression, invasion, metastasis, and chemoradiotherapy resistance in tumors by interacting with c-Myc." (PMID 36195846, 2022). "Other lncRNAs have also been implicated to function as master regulators of overexpressed common coding genes involved in primary pan-cancer development and among these, PVT1, SNHG11 and MIR22HG are deduced to be key regulatory lncRNAs32." (PMID 35534592, 2022). "Recently, several studies have shown that PVT1 is involved in the clinical and pathological development of various cancers." (PMID 36195846, 2022). "A careful examination of some cell functions influenced by c-Myc-targeting PVT1 is warranted to provide more evidence for their impacts on cancer cells in the future." (PMID 36230902, 2022). "Plasmacytoma variant translocation 1 (PVT1) participates in the formation and progression of various cancers, including GC." (PMID 35664988, 2022). "Plasmacytoma variant translocation 1 (PVT1) is an intergenic lncRNA located on chromosome 8q24, a well-known cancer-associated region." (PMID 34322395, 2021). "Many studies have shown evidence of carcinogenic activity of PVT1 in various cancers, such as negatively modulating miRNA by acting as a competing endogenous RNA or acting as a sponge to promote tumor effects." (PMID 33926464, 2021). "PVT1 contributes to many aspects of cancer biology through a complex signal network, with a role in tumor growth, metastasis, and response to chemotherapy and radiotherapy." (PMID 34336125, 2021). "The prognostic value of common and cancer-specific differently expressed lncRNAs, such as PVT1, in cancer outcomes, was emphasized here." (PMID 34335862, 2021). "In a study focusing on ovarian cancer, gains localised to 8q24.21 were evident in 59% of samples and resulted in a significant overexpression of PVT1, suggesting gains within this region can be a crucial factor of elevating lncRNAs in cancer." (PMID 33499210, 2021).
cancer (continued). "Prior studies have demonstrated that PVT1 is an important oncogene and plays critical roles in onset and development of various cancers." (PMID 34321604, 2021). "Many studies have reported that PVT1 overexpression was related to cancer growth and proliferation in vivo and in vitro." (PMID 34336125, 2021). "And the molecular functions of lncRNA PVT1 in those cancers have been intensely investigated, which emphasized the important role of lncRNA PVT1 in various tumorigeneses." (PMID 34805417, 2021). "Aberrant expression of PVT1 and its ability to regulate several miRNAs are hallmarks of cancer invasion and progression." (PMID 34131106, 2021). "Plasmacytoma variant translocation 1 (PVT1), whose role was more pronounced in several cancers, was also shown to contribute in fibrotic liver tissues via downregulation of PTCH1 expression and positive regulation of the Hedgehog pathway." (PMID 33622377, 2021). "Previous meta-analysis also reported that cancer patients with high PVT1 expression had a poorer overall survival (HR = 2.07, 95% CI: 1.40-2.74, P = 0.000) and a worse disease-free survival (HR = 2.10, 95% CI: 0.96-3.23, P = 0.000)." (PMID 34900027, 2021). "We first analyzed, by ddPCR expression of several cancer-associated lncRNAs (MALAT1, NEAT1, HOTAIR, H19, PVT1, MEG3) in both FNAs and surgical specimens and selected MALAT1, HOTAIR, and PVT1 as cancer biomarkers." (PMID 33030666, 2021). "Overexpressed PVT1 can suppress the binding of YTHDF2 with PVT1 to promote cancer cell proliferation." (PMID 35004679, 2021). "It is possible that PVT1 acting as a sequester for miRNA-186 leading to inhibition of its activities, affecting proliferation, invasion, and metastasis of cancer." (PMID 34200314, 2021). "PVT1 is amplified in many cancers and has been reported to function as a microRNA sponge ultimately inducing proliferation and suppressing apoptosis in cancer cells." (PMID 34386489, 2021). "In particular, we analyzed, by Droplet Digital PCR (ddPCR), six cancer-associated lncRNAs (MALAT1, NEAT1, HOTAIR, H19, PVT1, MEG3) in both FNAs and surgical tissues." (PMID 33030666, 2021). "Recently, lncRNAs including PVT1, LINC00963, and HOTAIR have been reported to be associated with radioresistance in many types of cancers." (PMID 33573349, 2021). "PVT1 was shown to be an important oncogenic lncRNA that was overexpressed in many cancers, including PC." (PMID 34828307, 2021). "There is a paucity of literature on the correlation between PVT1 and miRNA-186 as an important diagnostic and prognostic parameter in CRC and other cancer types." (PMID 34200314, 2021). "Plasma cell tumor heterotopic gene 1 (PVT1) is an intergenic long non-coding RNA that is aberrantly expressed in different cancers." (PMID 32156248, 2021). "The role of PVT1 has been explored in several cancers such as leukemia, colon, hepatocellular, breast, lung, and ovarian cancers." (PMID 34322395, 2021). "All integrations in the cancer samples occurred within or near the cancer-related genes PVT1, WAC and miR-205." (PMID 34175494, 2021). "Others have been implicated in diseases such as cancer, including metastasis associated lung adenocarcinoma transcript 1 (MALAT1) and plasmacytoma variant translocation 1 (PVT1)." (PMID 34940760, 2021). "Certainly, identifying the carcinogenic role and molecular mechanism of PVT1 has important implications for therapeutically targeting cancer." (PMID 34760707, 2021). "Three thyroid-specific genes (TG, TPO, and NIS), six cancer-associated lncRNAs (MALAT1, NEAT1, HOTAIR, H19, PVT1, MEG3), and two housekeeping genes (GAPDH and P0) were analyzed using Droplet Digital PCR (ddPCR)." (PMID 33030666, 2021). "The lncRNA PVT1 was found to be related to the MYC oncogene, and both are located within the 8q24.21 genomic region; PVT1 undergoes a copy number increase in many human cancers." (PMID 34940760, 2021).
cancer (continued). "Identification of transcriptional inhibition of tumor suppressor genes by PVT1 highlights the pathway to the investigation of mechanisms that lie behind the oncogenic role of PVT1 in cancer." (PMID 33430890, 2021). "As a lncRNA, PVT1 can also affect miRNAs directly, acting as a molecular sponge to regulate cancer cell development similar to miR-195 in osteosarcoma." (PMID 32156248, 2021). "Epithelial-mesenchymal transition (EMT) is a critical process that occurs in many types of cancers, and PVT1 has been shown to be involved in EMT induction." (PMID 33801373, 2021). "PVT1 is an oncogenic lncRNA involved in a variety of cancer types, correlates with the copy number of the MYC oncogene." (PMID 33777808, 2021). "Very interestingly, we found that higher expression of PVT1 mRNA correlates to shorter progression-free survival time in patients with stage 3/4 cancer and grade 3 OV." (PMID 33391456, 2021). "As defined for lncRNA, the upregulation of PVT1 (cg24514600) is proved to promote cancer cell proliferation, invasion, metastasis, and drug resistance." (PMID 34238128, 2021). "The biofunction “development of carcinoma” was one of the top cancer-related enriched biofunctions (p-value of 0.0176), with 8 DE lncRNAs: PVT1, CASC2, PCA3, EPB41L4A-AS1, C10orf25, CYTOR, FOXD2-AS1, and CRNDE." (PMID 33926464, 2021). "Further studies on the cell cycle regulation by PVT1 in cancer are required for better comprehension on its function." (PMID 32117705, 2020). "PVT1 is a well-known oncogene and correlated with a variety of cancers according to both the lncRNADisease 2.0 knowledgebase and the GeneCards database." (PMID 33318305, 2020). "Currently, there is no one precise PVT1 mechanism of action that is unique to all the cancers, although there is frequently cancer progression when PVT1 is upregulated." (PMID 32117705, 2020). "Altogether, PVT1 has been shown to be a promising target for treating drug resistance in cancer therapy." (PMID 32117705, 2020). "PVT1 is elevated in MM and coamplified with MYC in many cancers; there is an association between PVT1 expression level and poor prognosis in many cancers." (PMID 32992461, 2020). "PVT1 and c-Myc are both located on the 8q24 chromosomal locus (a frequent site for copy number gain and alterations in cancer)." (PMID 32117705, 2020). "Although PVT1 contributed to the regulation of cell proliferation in cancer cells, the mechanisms by which PVT1 regulates cell proliferation in NPC remained unclear." (PMID 31320749, 2020). "In fact, several lncRNAs affected by cancer-relevant SNPs or amplifications and deletions, including H19, PVT1,or ANRIL have been implicated in cancer drug resistance, as extensively reviewed elsewhere." (PMID 33329688, 2020). "In particular, the function of PVT1 has been reported in various cancer types and summarized in several review papers." (PMID 32499447, 2020). "Among the regions shortlisted using our approach, we found some previously characterized cancer-related lncRNAs such as PVT1, localized downstream of the MYC locus, or CCAT1/CARLo-5, located in an amplified region upstream of the MYC locus." (PMID 32858747, 2020). "Plasmacytoma variant translocation 1 (PVT1) is a highly conserved lncRNA, which is located downstream of MYC gene and is frequently co-amplified with MYC in several cancer types." (PMID 32154165, 2020). "Many studies have demonstrated that PVT1 is upregulated in a variety of human cancers, including GAC tissues and cell lines, non-small cell lung cancer, cervical cancer, and colorectal cancer, and serves as an onco-lncRNA in several tumor types." (PMID 33076512, 2020).